IL22 (interleukin 22)
Diseases named in the same sentence as IL22 in open-access papers (continued):
Sharing a sentence is not in itself a finding about the gene and the disease.
psoriasis (continued). "In psoriasis, Th17 cytokines IL-17 and IL-22 induce and maintain the expression of AMPs, and these processes in turn lead to increased generation of complexes with DNA." (PMID 36633910, 2023). "Among all the inflammatory stimuli responsible for the development of psoriasis, interleukin 22 (IL-22) can induce an imbalanced keratinocytes proliferation and differentiation." (PMID 38041107, 2023). "Described as a proinflammatory cytokine produced by CD4 memory T cells (e.g., Th1, Th17, Th22), IL-22, a member of the IL-10 family, have been found to be significantly elevated in patients with psoriasis compared to healthy controls." (PMID 37546687, 2023). "For psoriasis, Treg abundance will deactivate Th17 response via their released cytokines such as IL-22, IL-17, and IL21, which ultimately inhibit epidermal keratinocyte proliferation." (PMID 37270497, 2023). "In our study, we treated psoriasis-induced mice and IL-22- or TNF-α-stimulated HaCaT cells with SFN and subsequently measured the activation status of the STAT3 and NF-κB pathways." (PMID 38007430, 2023). "It has been reported that mast cells have been identified as the major source of IL-22 in patients with dermatitis and psoriasis." (PMID 37933011, 2023). "A plausible mechanism through which GLP-1 improves psoriasis is by blocking expression of IL-17, IL-22, IL-23 and TNF-α through the IL-23/Th-17 pathway." (PMID 37266425, 2023). "Previous research indicated that interleukin-17A (IL-17A), interleukin-22(IL-22), tumor necrosis factor-α (TNF-α), and interleukin-1α (IL-1α) were pro-inflammatory cytokines in psoriasis and linked with NF-κB signalling activation." (PMID 37636269, 2023). "The presence of antibodies against IL-22 has only been reported in the psoriasis and in the patients with autoimmune polyglandular syndromes." (PMID 37663050, 2023). "On the other hand, TNF-α, IL-23, IL-17 and IL-22 were reported to be fundamental in the pathogenesis of psoriasis." (PMID 37763769, 2023). "The activated immune cells then secrete pro-inflammatory cytokines IL-17 and IL-22 to contribute to psoriasis progression." (PMID 35869084, 2022). "Here, we review the current knowledge regarding Th22 cells and their main functional cytokine IL-22, especially their interaction with keratinocytes, in the pathogenesis of psoriasis, atopic dermatitis, lupus erythematosus, and other skin immune diseases." (PMID 35911703, 2022). "Th17 cells, which are known to play an essential role in immunological disturbances in psoriasis, secrete IL-22." (PMID 36226313, 2022). "Then, we verified the results in psoriatic lesions and a psoriasis model in vitro by stimulating keratinocytes with IL-17A, IL-22, IL-1α, oncostatin M, and TNF-α (M5)." (PMID 35586566, 2022). "Anti-IL-22 (median: 262.8 vs.190.5, p = 0.0418) antibody was decreased whereas anti-IL-15 (median: 25.5 vs. 30.5, p = 0.0069) was increased in psoriasis patients compared to that in healthy controls." (PMID 36118416, 2022). "Consistent with the ameliorated psoriasis‐like phenotype, the mRNA levels of genes related to the IL‐23/IL‐17 axis, such as Il23a, Il17a, and Il22, and the expression of Tnfa, Il6, and Il1b was decreased in the skin." (PMID 34936223, 2022). "For instance, elevated IL-22 levels have been observed in both skin lesions and blood, the strategy of blocking IL-22 in the treatment of psoriasis failed in a clinical trial." (PMID 35769988, 2022). "Although studies have been limited, recent research has proposed a difference in TNF-α, IL-17, IL-22 expressions in pediatric psoriasis patients compared with those in adult psoriasis patients." (PMID 36232430, 2022). "Cytokines implicated in psoriasis pathogenesis mainly IL-17, IL-23, TNF-α, IL-1, IL-22, IFN-α and IFN-γ are linked to JAK-STAT pathway." (PMID 35265634, 2022). "Strikingly, Mashiko proposed that mast cells were major IL-22 producers in psoriasis patients and atopic dermatitis individuals." (PMID 35911703, 2022).
psoriasis (continued). "Th17 cells with their derived cytokines, IL-17 and IL-22, participate in the progression of psoriasis by inducing inflammation and keratinocyte proliferation." (PMID 35209199, 2022). "There is emerging evidence that Th22 cells and IL-22 are involved in the development of skin diseases, particularly psoriasis and AD." (PMID 35911703, 2022). "Along with IL-22, IL-17, the primary effector of Th17 cells, also seemed necessary to induce IL-23-mediated murine psoriasis." (PMID 35911703, 2022). "Strikingly, the proportion of IL-22-producing mast cells occupied 20–80% in patients with psoriasis, and skin mast cells expressed IL-22 and IL-17 mRNA." (PMID 36242051, 2022). "Under the condition of abundant IL-23 in psoriasis lesional skin, some macrophages possibly produce IL-17A, IL-22 and IFN-γ in addition to TNF-α." (PMID 35837394, 2022). "Pediatric psoriasis patients exhibited a distinct difference in the expression of interleukin (IL)-17 and IL-22 compared to that of healthy pediatric controls and adult psoriasis patients." (PMID 36232430, 2022). "The expression of TNF-α and IL-6 as well as IL-22, IL-23, and IL-17 family of cytokines (IL-17A, IL-17E, and IL-17F) was significantly increased in psoriasis skin lesions." (PMID 35663991, 2022). "Recent advances in understanding molecular and cellular pathways have identified tumor necrosis factor-α (TNF-α), interleukin-17 (IL-17), IL-23, IL-22 as major contributors in psoriasis pathogenesis." (PMID 35265634, 2022). "In line with earlier findings of increased frequencies of IL-17A and IL-22 producing cells in psoriasis and PsA, we also found increased numbers of Th17 cells (metaclusters 1) in both psoriasis and PsA patients compared to healthy controls." (PMID 35045868, 2022). "Herein, we found serum levels of IL-12B (median: 6.16 vs. 9.03, p = 0.0194) and Th17 cytokines (IL-17A: median: 0.32 vs. 1.05, p = 0.0026; IL-22: median: 4.41 vs. 4.41, p = 0.0120) were increased in psoriasis patients." (PMID 36118416, 2022). "Collectively, both IL-22-producing Th17 cells and Th22 cells play important roles in psoriasis patients." (PMID 35911703, 2022). "Our study demonstrated that the oral administration of 10 mg/kg DXM alleviated the symptoms of psoriasis and inhibited keratinocyte proliferation by decreasing proinflammatory cytokines and IL-17- and IL-22-producing γδ T cell production." (PMID 35629363, 2022). "Previous studies have demonstrated that IL-22 is involved in immune diseases, such as psoriasis, systemic erythema, hepatitis and rheumatoid arthritis, and colitis." (PMID 36092152, 2022). "For example, Fania reported that three psoriasis patients developed psoriasiform skin lesions with augmented expression of IL-22 after receiving adalimumab." (PMID 35911703, 2022). "A mechanistic study on triptolide action was performed on IL-22-treated HaCaT cells, an in vitro model for keratinocytes in pathological lesions of psoriasis." (PMID 36613560, 2022). "IL17- and IL-22-dependent induction of psoriasis-like skin inflammation upon injection of IL-23 into mouse ears highlights the role of IL-23, IL-17 and IL-22 as master regulators in psoriasis." (PMID 35812457, 2022). "STAT3 conveys signals from psoriatic cytokines, such as IL-6, IL-17, IL-21, IL-22, and IL-23, to the nucleus and triggers an inflammatory response, which is involved in the pathogenesis of psoriasis." (PMID 35116069, 2022). "Studies indicate that IL-22 serum levels in psoriasis and rheumatoid arthritis patients are much higher than that the health individuals, and these also correlate with the disease severity." (PMID 35967401, 2022). "A mixture of five inflammatory molecules (TNF-α, IL-1α, IL-17A, IL-22, and oncostatin M; 10 ng/mL each) was used to stimulate HaCaT cells to mimic the microenvironment of psoriasis." (PMID 35209199, 2022). "We herein showed that of 13 ACAAs examined in this study, only anti-IL-22 and anti-IL-15 in psoriasis differed from those in controls." (PMID 36118416, 2022).
psoriasis (continued). "Individuals with psoriasis had elevated IL‐22 production by AOAH‐responsive circulating CD1a‐reactive T cells." (PMID 34913478, 2022). "Inhibition of IL-22 biological activity can also reduce the severity of psoriasis, which is also consistent with the psoriasis like symptoms in IL-22 transgenic mice." (PMID 35967401, 2022). "Circulating AOAH‐responsive CD1a‐reactive T cells from patients with psoriasis showed elevated IL‐22 production." (PMID 34913478, 2022). "In last few years, advances in understanding molecular and cellular pathways have identified tumor necrosis factor-α (TNF-α), interleukin-17 (IL-17), IL-23, IL-22 as major contributors in psoriasis pathogenesis." (PMID 35265634, 2022). "One of the sources of IL-17A in psoriasis is Th17 cells, then they are stimulated to secrete further cytokines by IL-23, which include (besides IL-17A): IL-17F, IL-21, IL-22, IL-26, and TNF-α." (PMID 36226313, 2022). "A 2D visualization of psoriasis RNA-seq datasets was unable to prove the relationship between IL-17A and IL-22, which indicated alternative sources of IL-22 such as Th22 or non-T cells rather than Th17 in psoriasis." (PMID 35911703, 2022). "Our result coincided with the finding that IL-17A- and IL-22-producing T cells in the peripheral blood of psoriasis patients play a critical role in affecting dermal inflammation." (PMID 35629363, 2022). "Of 13 anticytokine antibodies, anti-IL-22 was moderately lower (median: 262.8 vs.190.5, p = 0.0418), and anti-IL-15 was slightly higher (median: 25.5 vs. 30.5, p = 0.0069) in psoriasis than controls." (PMID 36118416, 2022). "Elevated expression levels of IFN-α, IFN-γ, IL-22, and IL-17 have an exacerbating effect on the skin epidermis by stimulating an increased inflammatory response, which can exacerbate psoriasis-like symptoms in the skin." (PMID 35566346, 2022). "In other studies, examination of the effect of curcumin on PBMC of psoriasis patients showed reduced T cell proliferation and production of cytokines, such as IFNγ, IL-17, GM-CSF and IL-22." (PMID 36613560, 2022). "As for circulating lymphocytes, CD4+/IL-17+ and CD4+/IL-22+ T-lymphocytes have been investigated with great interest because of their role in skin infection and in the skin of patients with psoriasis." (PMID 35722498, 2022). "CD1a‐autoreactive T cells from psoriasis patients showed elevated IL‐22 expression in the presence of AOAH, which was enriched in psoriatic lesions." (PMID 34913478, 2022). "We determined the expression levels of IL-17A and IL-22 in TCRγδT cells in the spleens of psoriasis-like mice after treatment with DXM using flow cytometry." (PMID 35629363, 2022). "Activation of PI3K and STAT3 promotes the excessive proliferation and abnormal differentiation of KC, infiltration of inflammatory cells, and secretion of cytokines (IL-6, IL-17, IL-22, and IL-23) in psoriasis." (PMID 35720176, 2022). "Other proinflammatory cytokines, including IFN-γ, TNF-α, IL-1β, IL-6, IL-22, IL-26, IL-29, or IL-36, have also been reported to play important roles in the development of psoriasis." (PMID 35313642, 2022). "Megna also discovered increased levels of IL-22 in psoriasis patients who switched to eczematous drug eruption after treatment of anti-IL-17 biologics." (PMID 35911703, 2022). "In line with this, IL-17- and IL-22-expressing NKp44+ ILC3s were identified in the blood and skin of psoriasis patients and were preferentially harbored in lesioned psoriasis skin." (PMID 34831296, 2021). "Transgenic overexpression of IL-22 in mice results in psoriasis-like skin alterations including hyperproliferation, acanthosis and hypogranularity." (PMID 34503066, 2021). "In the present study, we demonstrated that IFN-γ/IL-17A/IL-22 stimulation induce psoriasis-like changes in human keratinocytes." (PMID 33986690, 2021).
psoriasis (continued). "Stimulation with IFN-γ/IL-17A/IL-22 cytokine combination induced changes in the mRNA expression profile in human keratinocytes that mimic psoriasis-like transcriptional signature." (PMID 33986690, 2021). "Pediatric psoriasis patients exhibited a distinct difference in the expression of interleukin 17 (IL-17) and IL-22 compared to that of healthy pediatric controls and adult psoriasis patients." (PMID 34440145, 2021). "Earlier studies have revealed that IL-22 is highly expressed in chronic inflammatory conditions including psoriasis, IBD, and rheumatoid arthritis and induces expression of proinflammatory molecules like IL-6, IL-1, GM-CSF, and LPS-binding protein." (PMID 33451114, 2021). "To investigate the influence of ATG5 and paeonol intervention on psoriasis, we established an in vitro psoriatic model using IL-22/TNF-α stimuli and treated it with paeonol." (PMID 34113484, 2021). "Among various molecules associated with psoriasis, tumor necrosis factor (TNF)-α, IL-23, IL-17 and IL-22 are important regulators of psoriasis." (PMID 34134787, 2021). "Intriguingly, recent data from studies in mice indicates that tissue-resident innate lymphoid 3 cells (ILC3) also produce IL-17 and IL-22 cytokines in response to IL-23 signaling, which contributes to dermal inflammation in psoriasis." (PMID 34447766, 2021). "Animals developed psoriasis-like skin lesions after 5 weeks with increased infiltration of single IL-17+, IL-22+ or combined IL-17/IL-22+ CD4+ T cells." (PMID 34267743, 2021). "Further studies demonstrated that IL-22 also mediates IL-23/Th17 axis-induced psoriasis-like skin inflammation." (PMID 34975883, 2021). "In psoriasis, activated resident immune cells and keratinocytes can produce cytokines that initiate the inflammatory process such as IL-36, IL-23, and IL-22." (PMID 34884834, 2021). "IL-22 is produced by CD3-c-Kit+ cells in skin lesions of patients with psoriasis and AD, and c-Kit + FcεRI+ mast cells are the major cellular source of IL-22 in AD patients." (PMID 34208021, 2021). "Mast cells also propagate psoriasis by producing IL-17, and being a primary producer of IL-22 in psoriatic lesions." (PMID 34639182, 2021). "When IL-17F was studied in mice models of psoriasis, results showed that IL-17F-producing cells were more abundant than those producing IL-17A and IL-22." (PMID 34201664, 2021). "For example, IL-22, IL-23, IL-31, and IL-33 were increased in the skin of patients and model animals with allergic dermatitis, AD, and psoriasis." (PMID 33708782, 2021). "MiR-194-5p and GAB1 plasmid were co-transfected into IL-22-induced HaCaT cells to explore if miR-194-5p suppressed psoriasis progression via targeting and suppressing GAB1." (PMID 33393621, 2021). "The ILC3 subclass are disproportionately abundant in the blood and skin lesions of psoriasis patients and are classified by their production of IL-17 and IL-22, both cytokines that are key in the induction of keratinocyte proliferation." (PMID 34639182, 2021). "Interleukin-22 (IL-22) belongs to IL-10 superfamily, and the messenger RNA (mRNA) level of IL-22 was positively correlated with the severity of psoriasis." (PMID 33393621, 2021). "These cytokines affect the differentiation of the naive T cells into Th17 (T helper 17) cells, which produce interleukin IL-17 (interleukin 17) and IL-22 (interleukin 22), which lead to the development of psoriasis lesions." (PMID 33924414, 2021). "These elevated expression levels appeared consistent with previous studies that employed a similar IFN-γ/IL-17A/IL-22-induced psoriasis-like model in keratinocytes." (PMID 34834106, 2021). "We then investigated the effect of curcumol on viability and proliferation of NHEK cells stimulated with a combination of proinflammatory cytokines characteristic for psoriasis (IL-1α, IL-17A, IL-22, oncostatin M, and TNF-α; mix M5)." (PMID 34314383, 2021).
psoriasis (continued). "We evaluated serum levels of IL-17A and other cytokines, including IL-22 and IL-19,18 from the psoriasis molecular signature." (PMID 34643650, 2021). "The cartoon shows that treatment with pro-inflammatory molecules (like IL-22) modify the expression of different genes, known to be modulated in psoriasis." (PMID 33525692, 2021). "GAB1 expression was aberrantly up-regulated in lesional skin tissues of psoriasis patients and IL-22-induced HaCaT cells compared with that in healthy skin tissues and un-treated HaCaT cells." (PMID 33393621, 2021). "Psoriasis-like keratinocytes were generated by treating human primary keratinocytes with the psoriasis-associated cytokines IL-17A, TNF-α and IL-22." (PMID 33801280, 2021). "Classically, conventional CD4+ TH17 cells are believed to produce the effector cytokines IL-17 and IL-22 and are believed to trigger the pathogenesis of psoriasis in humans." (PMID 34831296, 2021). "Overall, our results point towards the implication of the passenger strand miR-21-3p in the onset of psoriasis in an IL-22-dependent manner." (PMID 34685526, 2021). "In psoriasis, IL-17-producing T helper cells (Th17) are central in the pathogenesis and Th17-related cytokines such as IL-17A, IL-17F and IL-22, together with TNFα, drive epidermal hyperplasia." (PMID 34616394, 2021). "Among them, serum IL-6 and IL-22 levels were considered to be positively correlated with the severity of psoriasis inpatients." (PMID 33685393, 2021). "Taken together, circ_0061012 silencing suppressed IL-22-induced proliferation and metastasis of keratinocytes through up-regulating miR-194-5p in psoriasis in vitro." (PMID 33393621, 2021). "In the present study, we have provided evidence for psoriasis-like changes in human keratinocytes as a result of IFN-γ/IL-17A/IL-22 stimulation." (PMID 34834106, 2021). "In contrast, psoriasis is associated with Th17 T-cells producing Th17 cytokines such as IL17A and IL22." (PMID 34445339, 2021). "Cytokines involved in the pathogenesis of psoriasis such as IL-17, IL-22 or IL-23 are also potential agents to evoke pruritus in psoriasis, but to date data on them in relation to pruritus are limited." (PMID 33467067, 2021). "Treatment of human keratinocytes with IL17A, TNF-α and IL-22 upregulates KRT17 by the transcription factor STAT3 that is constitutively phosphorylated in psoriasis." (PMID 33801280, 2021). "Both IL-22 and IL-17A promoted induction of AMP; they are implicated together in the inflammatory processes involved in cases of psoriasis, inflammatory bowel diseases, and rheumatoid arthritis." (PMID 34805416, 2021). "In psoriasis, IL-22 promotes proliferation and mobility of keratinocytes, preventing terminal differentiation as the cells progress through the dermis to the epidermis." (PMID 34868019, 2021). "Compared with healthy controls, psoriasis patients have upregulated levels of IL-22 and reduced levels of IL-22BP." (PMID 34868019, 2021). "The particular pathogenicity of TRM CD8 + in psoriasis is evidenced by the fact that they express the receptor for IL-23 and can produce pro-inflammatory IL-17 and IL-22 in the skin, even many months after the lesion has resolved." (PMID 34769769, 2021). "The authors stimulate HEKn cultures with IL-22 because this cytokine is a key cytokine in psoriasis." (PMID 34943117, 2021). "STAT3 mediates the signal of most cytokines in pathogenesis of psoriasis, including IL-23, IL-17A, IL-22." (PMID 34925011, 2021). "MiR-766-3p was upregulated in both HaCaT cells treated with the psoriasis-related cytokine pool (IL-17A, IL-22, IL-1 alpha, oncostatin M, and TNF-alpha) and tissues." (PMID 34992498, 2021). "Recently, mast cells have been shown to be the major producers of interleukin-22 in psoriasis and atomic dermatitis." (PMID 34134787, 2021).